CD82 (CD82 molecule)
Diseases named in the same sentence as CD82 in open-access papers (continued):
Sharing a sentence is not in itself a finding about the gene and the disease.
sarcoma (5 papers, 2012 to 2022). A usually aggressive malignant neoplasm of the soft tissue or bone. "In sarcomas, Gp78 interacts with the transmembrane metastasis inhibitor KAI1 (also known as CD82), and inhibition of Gp78 can promote the accumulation of KAI1, lead to apoptosis, and reduce tumor metastasis." (PMID 36499442, 2022).
oral cancer (4 papers, 2021 to 2024). "Overexpression of CD82/KAI1 transduced into oral cancer cell lines can significantly inhibit cell invasion." (PMID 38534734, 2024). "CD82 is poorly understood in oral cancer, and there are limited studies on its role in oral squamous cell carcinoma (OSCC)." (PMID 38473906, 2024). "How does CD82 function in this upregulated oral cancer cell subtype to regulate their progression and metastasis?" (PMID 38473906, 2024). "Liprin-α1 inhibits the expression of metastatic suppressor CD82 in cancers such as oral carcinoma, and the expression of these proteins has been known to correlate negatively." (PMID 37335526, 2023).
triple-negative breast carcinoma (4 papers, 2017 to 2025). An invasive breast carcinoma which is negative for expression of estrogen receptor (ER), progesterone receptor (PR), and human epidermal growth factor receptor 2 (HER2). "This study investigates the hypothesis that palmitoylation-deficient CD82 mutants sensitize triple-negative breast cancer cells to chemotherapy by disrupting membrane microdomains and amplifying intrinsic apoptosis, thereby offering a novel combinatorial therapeutic strategy." (PMID 41415560, 2025). "This study investigates the role of CD82 palmitoylation in modulating chemosensitivity in triple-negative breast cancer (TNBC) cells." (PMID 41415560, 2025). "Noteworthy, out of these 10 tested genes, only KAI1/CD82 had an antisense lncRNA spanning its promoter and suppressing it in the triple-negative breast cancer cell line MDA-MB-231 cell line." (PMID 37990044, 2023).
atherosclerosis (3 papers, 2020 to 2022). A disease characterized by the build-up of fatty material and calcium deposition in the arterial wall resulting in partial or complete occlusion of the arterial lumen. "CD82 has one intron SNP rs730129 that is associated with atherosclerosis and other near-gene or intergenic SNPs that are associated with myocardial infarction, blood pressure, and platelet function tests." (PMID 33860000, 2021).
gastric tumor (3 papers, 2017 to 2022). "As a metastasis suppressor gene, CD82 is also closely related to the gastric tumor cell invasion and metastasis." (PMID 34222025, 2021). "For example, in gastric tumor cells, Vangl1 drives tumor cell invasiveness and metastasis and binds to the C-terminal domain of KAI1 (CD82), a tetraspanin glycoprotein." (PMID 35646914, 2022). "The increased miR-197 downregulates CD82 to activate EGFR-ERK1/2-MMP7 signaling pathway, thus having an effect on promoting gastric tumor cells invasion and metastasis." (PMID 34222025, 2021).
muscular dystrophy (3 papers, 2020 to 2025). Muscular dystrophy (MD) refers to a group of more than 30 genetic diseases characterized by progressive weakness and degeneration of the skeletal muscles that control movement. "CD82, associated with muscular dystrophy, inhibits myoblast proliferation when suppressed." (PMID 40943108, 2025). "CD82/Pax7-positive target populations might have translational potential for CRISPR/Cas9-mediated editing in the context of muscular dystrophies, insofar as HDR in differentiated skeletal muscle remains challenging." (PMID 38020204, 2023).
renal cell carcinoma (3 papers, 2017 to 2022). "However, the function of CD82 and its underlying anti-metastasis role in renal cell carcinoma (RCC) is still unraveled." (PMID 28881668, 2017).
teratoma (3 papers, 2022 to 2025). A non-seminomatous germ cell tumor characterized by the presence of various tissues which correspond to the different germinal layers (endoderm, mesoderm, and ectoderm). "In the current study, we have demonstrated that an expandable and engraftable CD82+ERBB3+NGFR+ skeletal myogenic progenitor population can be produced from human PSCs via teratoma formation." (PMID 36766703, 2023). "We further revealed ERBB3 and CD82 as effective surface markers for prospective isolation of teratoma-derived skeletal myogenic progenitors." (PMID 35563894, 2022). "Nevertheless, when combined with CD82 and ERBB3, the use of NGFR further purified the skeletal myogenic population in human teratomas." (PMID 36766703, 2023). "Taken together, these results suggested that ERBB3 and CD82 were effective surface markers for identifying and isolating human PSC-derived skeletal myogenic progenitors produced via teratoma formation." (PMID 35563894, 2022). "Teratomas were enzymatically digested and mechanically dissociated to produce a single-cell suspension, stained for CD82, ERBB3, and NGFR, and the triple-positive population, representing approximately 2% of total teratoma-derived cells, isolated by fluorescence-activated cell sorting (FACS)." (PMID 40801582, 2025).
benign breast disease (2 papers, 2019 to 2021). "KAI1/CD82 expression was apparently lower in tumors than in adjacent tissues and benign breast disease tissues." (PMID 34306081, 2021).
Duchenne muscular dystrophy (2 papers, 2019 to 2020). Duchenne muscular dystrophy (DMD) is a neuromuscular disease characterized by rapidly progressive muscle weakness and wasting due to degeneration of skeletal, smooth and cardiac muscle. "Importantly, CD82 expression is reduced in cell lines and muscle tissue from Duchenne muscular dystrophy (DMD) patients, suggesting that its expression is affected by loss of dystrophin." (PMID 33243288, 2020). "Our previous study identified CD82 as an effective marker to prospectively isolate human muscle stem cells and found its expression variably decreased in cell lines and muscle tissues from patients with Duchenne muscular dystrophy." (PMID 33243288, 2020). "The muscles from patients with Duchenne muscular dystrophy (DMD) commonly showed a reduced expression of CD82, which suggests that this molecule may play essential roles of SMPC function in the process of muscle degeneration." (PMID 31828070, 2019).
epidermoid carcinoma (2 papers, 2021 to 2025). "We also question the implication of GSL that are known to play an important role in the organization of CD82-enriched microdomains and can modulate cell motility in epidermoid carcinoma cells." (PMID 34207462, 2021).
glaucoma (2 papers, 2021 to 2022). Increased pressure in the eyeball due to obstruction of the outflow of aqueous humor. "Here, we induced CD82 overexpression in a more dramatic injury model, namely, optic nerve crush (ONC), which led to evident neuronal loss and rapid axonal damage by directly interrupting axoplasmic transport comparable to advanced glaucoma." (PMID 34897284, 2021). "In addition, we illustrated the pro-regenerative effects of CD82 in a more severe injury model of ONC in which axon loss and RGC death were apparent due to complete axoplasmic flow disruption comparable to advanced glaucoma." (PMID 34897284, 2021). "Although several studies have suggested that CD82 not only inhibits EMT in various cancers but also attenuates glaucoma and OIR in vivo, no studies have established the potential of CD82 in the EMT of RPE cells." (PMID 36386228, 2022).
kidney cancer (2 papers, 2014 to 2024). Primary or metastatic malignant neoplasm involving the kidney. "Several genes showed a low gDS in most kidney cancer cell lines, such as CD82, CD7, MEST, SELP, BMP6, CA2, DNAJC6, and VEPH1." (PMID 38728235, 2024).
lymphoid tumor (2 papers, 2019 to 2021). "It is possible that decreased amounts of CD82 within exosomes might be due to redistribution from tumour tissues and it might be associated with drug resistance through promotion of metastasis and tumour cell survival in lymphoid tumours." (PMID 31034520, 2019). "For example, CD82 is not expressed in lymphoid tumor cells but is overexpressed in the EVs derived from these very same lymphoid cells." (PMID 33808296, 2021). "Since expression of CD82 within exosomes has not been reported in lymphoid tumours, this is a newly identified exosomal protein that might be associated with drug resistance in these tumours." (PMID 31034520, 2019).
pancreatic adenocarcinoma (2 papers, 2017 to 2018). "In this study, we identify tetraspanin CD82 (also called KAI1) as a component of the promiscuous TIMP-1 interacting protein complex on cell surface of human pancreatic adenocarcinoma cells." (PMID 28030805, 2017).
pancreatic ductal adenocarcinoma (2 papers, 2017 to 2018). An infiltrating adenocarcinoma that arises from the epithelial cells of the pancreas. "TIMP-1 and CD82 expression status in patients with pancreatic ductal adenocarcinoma (PDAC) might demonstrate future usefulness as a differentiation marker and give us new insight into tumorigenic metastatic potential." (PMID 28030805, 2017). "Co-localization of TIMP-1 and CD82 observed in breast ductal carcinoma and pancreatic ductal adenocarcinoma may arise from this." (PMID 28030805, 2017). "In vivo, biopsies from patients diagnosed with breast ductal carcinoma in situ (DCIS) and pancreatic ductal adenocarcinoma (PDAC) were immunostained with antibodies against TIMP-1 and CD82." (PMID 28030805, 2017).
papillary carcinoma of the thyroid (2 papers, 2014 to 2022). "In addition, HGF stimulation of papillary carcinoma of the thyroid (PTC) cells causes up-regulation of COX-2 and down-regulation of CD82/KAI-1; both these molecules have a major role in controlling tumor cell invasiveness." (PMID 28548071, 2014).
rheumatoid arthritis (2 papers, 2021 to 2023). A chronic, systemic autoimmune disorder characterized by inflammation in the synovial membranes and articular surfaces. "As it was shown on the mouse model of rheumatoid arthritis (chronic autoinflammatory joint disease), the level of CD82 is increased in RASF (rheumatoid arthritis synovial fibroblasts), where it plays an important role in cell adhesion and motility." (PMID 33923295, 2021). "Interestingly, it has been shown that cartilage invading synovial fibroblasts in rheumatoid arthritis express CD82 and it is hypothesized that CD82 expression reduces their motility once they are within the cartilage, keeping these invading cells at the site of destruction." (PMID 37357305, 2023).
Sepsis (2 papers, 2020 to 2025). Sepsis is defined as life-threatening organ dysfunction caused by a dysregulated host response to infection. "The nomogram illustrates the individual contributions of the five genes (TXN, MAPK14, WIPI1, CD82, and NEDD4) and clinical information (age, gender) to the overall risk score, providing a practical tool for estimating the probability of sepsis." (PMID 40299574, 2025). "For example, TXN and MAPK14 are expressed predominantly in monocytes, whereas WIPI1, CD82, and NEDD4 exhibit variable expression in T and B cells, highlighting the diversity and composition of immune populations during sepsis." (PMID 40299574, 2025). "The merged dataset (GSE57065 and GSE65682) revealed that all five genes (CD82, MAPK14, NEDD4, TXN, and WIPI1) were significantly upregulated in the sepsis group compared with the control group." (PMID 40299574, 2025). "It associates directly with TDRD9 and indirectly with SLC16A3 in pediatric sepsis, through MTF1, CD82, and G6PD." (PMID 32318053, 2020).
acute lymphoblastic leukemia (1 paper, 2021). Leukemia with an acute onset, characterized by the presence of lymphoblasts in the bone marrow and the peripheral blood. "KAI1/CD82 may also serve an important role in the evolution of pediatric acute lymphoblastic leukemia (ALL)." (PMID 34306081, 2021).
allergic reactions (1 paper, 2014). "In T cells, several tetraspanin proteins, including CD9, CD81 and CD82 are reported to associate with CD4 or CD8 and enhance T cell effector functions, while CD81 negatively modulates FcεRI-mediated degranulation in mast cells and suppress IgE-dependent allergic reactions." (PMID 24832104, 2014).
anaplastic cancer (1 paper, 2022). "The reduction in CD82 levels may be related to the increased metastatic potential which is characteristic of anaplastic cancers." (PMID 35328683, 2022).
atopic dermatitis (1 paper, 2023). "The expression of the tetraspanins such as CD9, CD37, CD53, CD63, CD81, and CD82 on FcεRIpos skin dendritic cells (DCs) from atopic dermatitis patients is significantly higher when compared to skin DCs of not allergic healthy individuals." (PMID 36672710, 2023).
breast tumours (1 paper, 2020). "In breast tumours, CD82 reduces in vitro migration and in vivo metastasis." (PMID 32410585, 2020).
Candidemia (1 paper, 2022). A form of invasive candidiasis where species of CANDIDA are present in the blood. "Accordingly, Cd82−/− mice fail to control fungal growth and exhibit greater susceptibility in vivo and polymorphisms in the CD82 gene are associated with development of candidemia in patients." (PMID 34964702, 2022).
Cognitive impairment (1 paper, 2022). Abnormal cognition is characterized by deficits in thinking, reasoning, or remembering. "In addition, increasing cleavage of TRPM7 α‐kinase by CD82 has been shown to induce numb phosphorylation at T346S348 and promoted Aβ secretion, which suggests that elevated CD82‐TRPM7‐Numb signal may be associated with cognitive impairment." (PMID 36401602, 2022).
colitis (1 paper, 2024). Inflammation of the colon. "Observations show that CD82 inhibits NLRP3 inflammasome activation both in vitro and in vivo, and in rodents, CD82 deficiency reduces the severity of colitis." (PMID 38892354, 2024). "As a result, administering B. vulgatus to rodents with colitis improved survival by mediating CD82 expression and activating NLRP3." (PMID 38892354, 2024). "Suppression of CD82 decreased the pathogenesis of colitis by increasing NLRP3 inflammasome activation via BRCC3-dependent K63 deubiquitination." (PMID 38892354, 2024).
experimental autoimmune encephalomyelitis (1 paper, 2019). An autoimmune demyelinating disease of the central nervous system that is produced experimentally in animals by the injection of homogenized brain or spinal cord in Freund's adjuvant. "Encephalitogenic T cells from Myelin Oligodendrocyte Glycoprotein (MOG)-Induced Experimental Autoimmune Encephalomyelitis (EAE) mice showed significantly lower levels of TSPAN32 and increased levels of CD9, CD53, CD82 and CD151." (PMID 31487788, 2019).
fibrosis (1 paper, 2020). the formation of excess fibrous connective tissue in an organ or tissue in a reparative or reactive process. "Collectively, these data show a Cd82+Prgfra+ fibroblast in murine and human pulmonary fibrosis and demonstrate that CD82 marks distinct myofibroblast and fibroblast populations across visceral and localised human fibrosis." (PMID 32488016, 2020). "Nonetheless, the differential expression of CD82 on fibroblasts in visceral fibrosis and myofibroblasts in localised human fibrosis suggests discrete functions during fibrosis at different anatomical sites." (PMID 32488016, 2020).
fungal infection (1 paper, 2024). "We speculate that the upregulation of CD82 and S100A7 in CAL 27 is part of the cells’ reaction to a fungal infection." (PMID 38473906, 2024).
gastric ulcer (1 paper, 2011). An ulcerated lesion in the mucosal surface of the stomach. "All normal gastric epithelium and gastric ulcer tissues strongly expressed transcripts and proteins of CD9, CD63 and CD82 as compared with corresponding controls." (PMID 21521534, 2011). "All normal gastric epithelium and gastric ulcer tissues strongly expressed transcripts of CD9, CD63 and CD82." (PMID 21521534, 2011). "All normal gastric epithelium and gastric ulcer tissues were strongly expressed immunostaning of CD9, CD63 and CD82." (PMID 21521534, 2011).
Granuloma (1 paper, 2018). A compact, organized collection of mature mononuclear phagocytes, which may be but is not necessarily accompanied by accessory features such as necrosis. "CD82 expression was weakly positive in the cytosol of epithelial cells of bronchioles, pneumocytes, and smooth muscle cells of blood vessels from normal lung parenchyma; however, pulmonary TB showed strong positivity in epithelioid cells and multinucleated giant cells in granulomas." (PMID 29760437, 2018).
Huntington disease (1 paper, 2025). Huntington disease (HD) is a rare neurodegenerative disorder of the central nervous system characterized by unwanted choreatic movements, behavioral and psychiatric disturbances and dementia. "In addition, the pathway of huntington disease and parkinson disease highly expressed in CD82 and CDKN1A." (PMID 39966875, 2025).
ischemic stroke (1 paper, 2025). A stroke disorder caused by obstruction of blood flow to the brain, due to thrombotic (local blood clot formation) or embolic (due to a blood clot or other material traveling from another site) event. "Among them, FTH1, SLC40A1, NRAS, CD82, and PTPN18 emerged as potential key targets underlying the antiferroptotic effects of acupuncture on ischemic stroke." (PMID 40552324, 2025). "Bioinformatics analysis and RT-qPCR suggested that FTH1, SLC40A1, NRAS, CD82, and PTPN18 might serve as potential key targets underlying the antiferroptotic effects of acupuncture on ischemic stroke." (PMID 40552324, 2025). "The results demonstrated that the expression levels of FTH1, SLC40A1, NRAS, CD82, CD44, and PTPN18 were upregulated in mice with ischemic stroke following acupuncture treatment." (PMID 40552324, 2025). "Moreover, FTH1, SLC40A1, NRAS, CD82, and PTPN18 levels significantly increased after acupuncture in ischemic stroke mice." (PMID 40552324, 2025). "However, related studies on CD82-mediated ferroptosis regulation in ischemic stroke are lacking, and CD82 might be a novel target of acupuncture-mediated ferroptosis regulation in ischemic stroke." (PMID 40552324, 2025).
laryngeal squamous cell carcinoma (1 paper, 2014). A squamous cell carcinoma that arises from the larynx. "The purpose of our study is to explore the relationship between cancer stem cells (CSCs) marked by CD133 and KAI1/CD82 expression and the clinicopathological characteristics of patients with laryngeal squamous cell carcinoma (LSCC)." (PMID 24758564, 2014).
lymphoma (1 paper, 2023). A malignant (clonal) proliferation of B- lymphocytes or T- lymphocytes which involves the lymph nodes, bone marrow and/or extranodal sites.
metastatic colorectal cancer (1 paper, 2022). "In addition, ST6Gal1 promotes the exosome-mediated exporting of the metastasis suppressor Kang-Ai 1 (KAI1, also known as CD82), thereby reducing KAI1-mediated suppression of integrin signaling in human metastatic colorectal cancer cells." (PMID 36497322, 2022).
myeloma (1 paper, 2025). "In this context, 2 key myeloma markers, MYC and DKK1, as well as many other cancer-associated genes, including ADM, HDGF, IL15, HGF, STMN1, CDKN1B and CD82, were potentially regulated by the predicted ligands." (PMID 41056512, 2025).
nasopharyngeal carcinoma (1 paper, 2015). A carcinoma arising from the nasopharyngeal epithelium. "The aim of this study was to investigate KAI1/CD82 protein expression in human nasopharyngeal carcinoma (NPC) cell lines and human NPC tissues." (PMID 25789023, 2015).
Nodal marginal zone lymphoma (1 paper, 2021). "CD82 was over expressed in tissue samples of Nodal marginal zone lymphoma patients (NMZL)." (PMID 33921415, 2021).
ocular hypertension (1 paper, 2021). Abnormally high intraocular pressure. "Here, we explored the role of the tetraspanin superfamily member CD82 in an acute ocular hypertension model." (PMID 34897284, 2021).